IL6 (interleukin 6)
Diseases named in the same sentence as IL6 in open-access papers (continued):
Sharing a sentence is not in itself a finding about the gene and the disease.
tumor (continued). "Relative to the control group, the average tumor volumes of the tocilizumab group were significantly decreased, and IL6 in the peripheral blood serum was lower according to ELISA." (PMID 27163161, 2016). "In turn, paracrine IL-6 can induce autocrine IL-6 expression in cells within the tumor microenvironment, thus establishing an IL-6+ niche and enhancing tumor progression." (PMID 27190500, 2016). "DEN-induced tumor related inflammation was further promoted through increased protein concentrations of liver IL-6 and TNF-α as compared to WT during carcinogenesis initiation." (PMID 27494874, 2016). "Immunohistochemical analysis showed that IL-6, IL-6R and gp130 are highly expressed in tumor sections of the control NOD/SCID mice, while in sgp130-treated mice, their expression levels are significantly lower." (PMID 27080032, 2016). "Interleukin 17A (IL-17A), a pro-inflammatory cytokine secreted by CD4+ Th17 cells, triggers tumor cells to produce interleukin 6 (IL-6), which in turn activates STAT3-dependent survival and angiogenesis." (PMID 27341128, 2016). "We consistently observed that IL-6 treatment had increased overall tumor burden (as measured by radiance) starting at 48 days after cell engraftment." (PMID 27769047, 2016). "In the mouse model, SHH inhibitors significantly reduced tumor incidence and multiplicity, decreased the expression of IL-6, TNF-α, COX-2, STAT3, and NF-κB, and significantly induced apoptosis." (PMID 26716648, 2016). "Our results suggest IL-6 a mediator of these tumor promoting influences and is important for the IBC induced migration of MSCs." (PMID 27756885, 2016). "Recent studies have provided evidence that targeting the IL-6 trans-signaling pathway would be a valid anti-tumor approach." (PMID 27080032, 2016). "Together, these findings suggest that senescent stromal-derived IL-6 promotes tumour growth by driving accumulation of G-MDSCs." (PMID 27272654, 2016). "Lamina propria macrophages are constantly exposed to microbial products and are a major source of pro-inflammatory cytokines, such as TNF-α and IL-6, in the tumor microenvironment." (PMID 27679575, 2016). "Given that Selumetinib reportedly blocks production of the pro-cachectic inflammatory cytokine IL-6, we measured IL-6 in tissue, tumor and blood." (PMID 28149280, 2016). "It is generally believed that IL-6 produced in macrophages is one of the pro-inflammatory cytokines responsible for tumor progression, and is a key target gene of NF-κB p65." (PMID 27793010, 2016). "Increased expression of IL-6 is thought to act as a link between chronic inflammation and tumor development." (PMID 26883202, 2016). "The present paper is continuation of our previous findings concerning the role of selected inflammatory proteins, such as C-reactive protein (CRP), interleukin 6 (IL-6), hematopoietic cytokines (HGFs), and metalloproteinases (MMPs) as tumor markers for EC." (PMID 27041792, 2016). "Based on a previous report, we suspected that the clinical symptoms and abnormal laboratory findings were eventually dependent on IL-6 overproduction by the tumor." (PMID 27579040, 2016). "The least level of production of either IL-6 or TNF-α was by spleen cells from mock-vaccinated tumor-bearing mice." (PMID 27598146, 2016). "It has been found that senescent umbilical cord MSCs produce high amount of IL-6, which is shown to be major mediator of MSCs and tumor cells crosstalk." (PMID 27630452, 2016). "The data presented here establish an additional mechanism by which ESE3/EHF restrains stemness and tumor progression through repression of IL-6." (PMID 27732936, 2016).
tumor (continued). "Both of transgenic animals and in vitro investigations reported that overexpression of the canonical IL-6 signaling pathway is a major characteristic in human neoplasia and that oncogenic overexpression of this pathway can occur at many levels." (PMID 27285760, 2016). "PPIA can also be secreted into the circulation to attract monocytes and stimulates monocytes to produce IL-6, and thereby create a pro-tumor microenvironment." (PMID 26752561, 2016). "Elevated serum interleukin-6 (IL-6) levels correlates with tumor grade and poor prognosis in cancer patients." (PMID 27383632, 2016). "We first investigated the considerable initiating effect of IL6 during the hypoxia process, and we found that hypoxic pretreatment of tumor cells induced significant IL6 expression and autophagy activation." (PMID 27163161, 2016). "In this study, the reverse transcription polymerase chain reaction (RT-PCR) results showed that the mRNA levels of IL-6 were considerably increased on 16 days after tumor cell implantation (TCI)." (PMID 27267059, 2016). "As inflammatory tumor microenvironment including cytokines are orchestrated by NF-κB, we identified IL-6, IL-8 and MCP-1 as important downstream moleculars of NF-κB p65 for sustaining the phenotype and function of GC-MSC." (PMID 26934326, 2016). "IL-6 secretion by immune cells within the tumor microenvironment leads to accumulation of regulatory cells." (PMID 27413756, 2016). "This process was associated with higher numbers of bone marrow adipocytes expressing IL-6 in direct vicinity to tumor cells." (PMID 27049717, 2016). "Herein we demonstrate reciprocal tumor interactions through IL-6 with cells found in the IBC microenvironment." (PMID 27756885, 2016). "IL-6 signaling in tumor cells increases tumor growth by promoting tumor invasiveness, metastasis and angiogenesis." (PMID 27756885, 2016). "The cancer causing effects of BaP, such as increasing the expression of oncogenic entities miRNA-21 and IL-6 and decreasing the expression of the tumor suppressor miRNA-214, were mitigated by CUR and Nano-CUR." (PMID 26837852, 2016). "We also examined the production of tumor-promoting cytokines, such as TNFα or interleukin-6, by 4T1-sup-activated PEC." (PMID 26834744, 2016). "Growing evidence suggests that JAK2/STAT3 signaling can be activated by IL-6 and this activation is required for tumor initiation and progression." (PMID 27367272, 2016). "EGFR driven NSCLC tumors, in particular, have been demonstrated to secrete increased local concentrations of tumor promoting cytokines including IL-6, GCSF, and GM-CSF among others in the immediate tumor microenvironment." (PMID 27866514, 2016). "In tumor-bearing mice, IL-2, IL-6, IL-12, TNF-α, and MCP-1 were up-regulated while IL-10 was down-regulated after cGAMP treatment." (PMID 26754564, 2016). "RNA-sequencing analysis showed that TTP over-expression downregulates several tumor-related factors, including Pim-1 and IL-6." (PMID 26894969, 2016). "IL-1β was abundant in P29 tumours at the mRNA level, particularly in the peripheral region, in B6 mice compared with those tumours in IL-33−/− mice, and IL-4, IL-6 and TRAIL expression was quite low in both types of tumours." (PMID 26775708, 2016). "Fanny Chalmin demonstrated that mice tumor-derived exosomal HSP72 induce IL-6 production by MDSCs through activation of TLR2 and its adaptor MyD88, leading to Stat3 phosphorylation and the promotion of MDSC immunosuppressive functions." (PMID 27090786, 2016). "We verified the efficacy of anti-IL-1R1 in vivo by measuring the relative expression of IL-1-responsive genes and saw a significant reduction in the expression of Il6, Il1b and Ptgs2 in tumours from anti-IL-1R1-treated mice relative to IgG-treated mice." (PMID 27708283, 2016).
tumor (continued). "We further demonstrated the anti-angiogenic capacity of quininib by examining gene expression of angiogenic factors in xenograft tumours and found that the expression of IL6, IL8, NRP2, VEGFA and FGF1 was reduced by quininib treatment." (PMID 27739445, 2016). "Activated SIR interrelates increased c-reactive protein, circulating neutrophils, NLR, mGPS, IL-6, platelets, tumor necrosis and decreased albumin, lymphocytes, hemoglobin, peritumoral infiltrate, and of course poorer survival." (PMID 27992611, 2016). "Pro-inflammatory cytokines such as IL-5, IL-6 and IL-17 are capable of promoting tumour growth which were reduced significantly by Fe-bLf-Dox." (PMID 27576789, 2016). "TNF-α and IL-6, reported as regulatory cytokines in the tumor microenvironment, have also been revealed as potential prognostic serum biomarkers in early-stage HCC35." (PMID 27117207, 2016). "The levels of serum IL-6 and muscle-specific E3 ligases elevated by tumor burden were also considerably reduced by WCUP administration." (PMID 27064118, 2016). "Immune system promotes tumour vessel regeneration, migration, invasion, and metastasis by raising regulatory T lymphocytes and activation of related modulators such as IL-6 and TNF-α, C reactive protein, induction of neutrophilia, battering down immune system." (PMID 27732958, 2016). "Meanwhile, a heightened amount of neutrophils levers the up-regulation of cytokines and chemokines (interleukin-1, interleukin-6 (IL-6), or tumor necrosis factors), thus facilitating tumor proliferation." (PMID 27427969, 2016). "Overall, these results demonstrate short-term PDTC treatment to cachectic mice attenuated cancer-induced disruptions to muscle and liver signaling, and these changes were independent to altered tumor burden and circulating IL-6." (PMID 27449092, 2016). "A possible mechanism through which STAT3 is hyperactivated in tumors involves the autocrine production of IL-6 from tumor cells." (PMID 26888313, 2016). "The aim of this study is to characterize the mechanism by which ALV-J induces IL-6 expression, and the role of IL-6 in tumor development." (PMID 27852059, 2016). "In CC patients, high expression of IL-6 correlate with a promoting effect in tumor cell growth by autocrine and/or paracrine processes." (PMID 27220278, 2016). "Unfortunately, tumor irradiation increases the expression of various cytokines displaying these effects, including transforming growth factor-beta and interleukin-6." (PMID 27500125, 2016). "In absence of IFNγ, tumors were characterized by an important production of IL-17 and IL-6 by tumor infiltrating cells and tumor cells." (PMID 27589729, 2016). "For the tumor, an up-regulation of NFκB target genes was observed (e.g. IL-6, IL-8, ICAM1) as well as of cytokines typically expressed by epithelial cells or fibroblasts involved in the first events of an immune response." (PMID 27463372, 2016). "Among seven cytokines analyzed in the C3HBA tumor interstitial fluid, IL-6 was the only cytokine found to be significantly higher in the extracellular microenvironment in Chy tumors." (PMID 27329584, 2016). "Accordingly, secreted IL6 and IL6 promoter activity was elevated in cultured cells derived from tumours and metastases as well as in the serum of mice bearing HT-resistant xenografts (treatment with tamoxifen or fulvestrant)." (PMID 26858125, 2016). "There is also the effect mediated by IL-1, IL-6, IFNγ and TNFα, that increases the invasiveness of the tumor on bone tissue." (PMID 27821086, 2016). "In fact, AT is recognized now as potent endocrine organ by secreting pro-inflammatory cytokines (such as TNF-α and IL-6) and adipokines (such as leptin) in the tumor microenvironment." (PMID 27066006, 2016). "At present, little is known about the potential regulatory function of IL-6 in the activation of PD-1/PD-L1 tumor immunopathology." (PMID 26761210, 2016).
tumor (continued). "Inflammatory cytokines, such as tumor necrosis factor (TNF)-α, interleukin (IL)-1β and IL-6, produced by a tumor and/or activated by immune cells, have been shown to stimulate cancer cell growth and influence clinical disease status and prognosis." (PMID 26959121, 2016). "Proinflammatory factors IL-6 and IL-1β are secreted by many cell types, such as immune cells and tumor, stromal, and endothelial cells, which play an important role in inflammation-associated carcinogenesis." (PMID 27057094, 2016). "It is also worth noting that IL-6 signaling in the tumor microenvironment is actually increased after chemotherapy and directly contributes to chemoresistance." (PMID 27531896, 2016). "In the present study, we investigated the combination therapy of temozolomide and tocilizumab in our xenograft tumor models and subsequently examined the ability of anti-IL6 therapy to reduce temozolomide-induced autophagy and improve its efficiency in vivo." (PMID 27163161, 2016). "In PTC patients (N = 60), M ± SE of IL-6 mRNA expression in tumour and their adjacent normal tissues were 4969.46 ± 903.77 counts/mm2 and 1076.06 ± 301.70 counts/mm2, respectively." (PMID 27034885, 2016). "Taken together, these data support the conclusion that tumor-induced IL-6 is both necessary and sufficient to suppress the potential of the liver for ketogenesis." (PMID 27829137, 2016). "Treatment with these cationic polymers also down-regulated the serum levels of tumour-derived factors such as IL-6 and GM-CSF, further highlighting the potency of cationic materials in eliminating tumour-induced MDSCs." (PMID 27074905, 2016). "Although there was evidence supporting a role in T-cell activation and trafficking, IL-6 within the tumor microenvironment is generally considered as a malevolent player that promotes tumor progression." (PMID 27006530, 2016). "In SS patients, the levels of neopterin, ß2-MG and sIL-2R are significantly elevated, and IL-6 correlates with tumor burden." (PMID 27780938, 2016). "IL-6 is a pleiotropic proinflammatory cytokine with a wide range of biological activities in immune regulation, hematopoiesis, inflammation, and neoplasia and interleukin-6 demonstrates a strong correlation with fever." (PMID 27068222, 2016). "After 10 days post-injection of the cells pre-treated with IL-6 or vehicle control for 24 hours, animals were sacrificed and the lungs were microscopically examined for tumor nodules based on GFP marker and hematoxylin and eosin (H&E) staining." (PMID 27531896, 2016). "In the present study, we report a novel tumor-promoting mechanism of IL6 in which hypoxia-induced IL6 promotes tumor cell survival by upregulating autophagy in GBM through the p-STAT3-MIR155-3p pathway." (PMID 27163161, 2016). "It appears that IL-6, of all pro-inflammatory cytokines, plays a major role in modulating tumor progression." (PMID 27383632, 2016). "IL-6 is overexpressed in CRC tissues and elevated levels of serum IL-6 correlate with larger tumor size, occurrence of liver metastases, and reduced survival." (PMID 27148488, 2016). "IL10 and the gene encoding its receptor IL10R were expressed mainly by TAMs, LIF and LIFR by tumor cells, IL6 and the genes for IL6 receptor subunits IL6R and IL6ST by both cell types." (PMID 27215396, 2016). "IL-6 has been shown to promote tumor lymphangiogenesis through vascular endothelial growth factor-C (VEGF-C) induction in tumor cells." (PMID 27383632, 2016). "Although IL-6 has been well described as important factor in regulation of MSCs and tumor cells properties, its mechanisms of action in crosstalk of MSCs and tumor cells are still not completely understood." (PMID 27630452, 2016). "Inhibition of tumour growth in IL-6 knockout mice also indicates the role of IL-6 in stimulation of tumour development." (PMID 27538520, 2016).
tumor (continued). "Serum levels of IL-6, IL-8 and IL-10 were measured before surgery and anaesthesia, during tumour removal, at the end of surgery, and at 24 and 48 h after surgery." (PMID 27001425, 2016). "To confirm the active status of the IL-6-related feedback loop in CAFs, we decided to assess the levels of the components of this loop in CAFs as compared to their adjacent tumor counterpart fibroblasts (TCFs) from the same patients." (PMID 27248826, 2016). "In the immune system, non-canonical Notch signaling is involved in the activation and proliferation of CD4+ T cells as well as in the tumor-promoting effects of interleukin-6 (IL-6)." (PMID 27148486, 2016). "To further determine the role of osteopontin and IL-6 for the bone marrow tumor niche, we used osteopontin deficient (OPN-/−) mice and neutralizing IL-6 monoclonal antibody treatment, respectively." (PMID 27049717, 2016). "TANs have influence on tumour cells via oncostatin M which is a cytokine belonging to interleukin-6 (IL-6) family." (PMID 27212807, 2016). "Further, the current study observed significant higher cytoplasmic expression of IL-6 protein in the primary tumours of PTC patients than in the patients with benign thyroid disease patients." (PMID 27034885, 2016). "IL-6 and IL-12 mRNA expression was similarly up-regulated in whole tumour lysate-pulsed DCs, the production of high levels of IL-12 being characteristic of maturing DCs at the initial state of naïve T cell-DC interaction." (PMID 26795765, 2016). "Our results suggest IL-6 is a mediator of these tumor promoting influences and is important for the IBC induced migration of MSCs." (PMID 27756885, 2016). "Our microarray and qRT-PCR data suggested that metastatic tumor cells possess higher expression levels of endogenous IL-6 and IL-1β and their receptors." (PMID 27698389, 2016). "Among the cytokines reported so far, interleukin-6 (IL-6) is one of the pivotal proinflammatory cytokines presented in the tumor microenvironment." (PMID 27769047, 2016). "There is growing body of evidence demonstrating that IL-6 plays a vital role in various aspects of tumor behaviors including cell proliferation, migration, invasion, differentiation, and angiogenesis." (PMID 27267059, 2016). "Externally applied onto the acupoints, Nidus Vespae is experimentally proven to increase TNF-α and IL-6 secretion of monocytes and the IgG production of B cells and promote the phagocytosis of tumor cells by monocytes, effects similar to the SMS herbal remedy." (PMID 27190532, 2016). "Here we showed that adipocytes in the vicinity of the tumor cells express large amounts of IL-6, which can promote tumor growth." (PMID 27049717, 2016). "The ensuing anemia is refractory to oral iron therapy and can be reversed by resection of the tumor, which eliminates the hepcidin inducer (IL-6)." (PMID 27445804, 2016). "MSC and macrophages grown in co-culture produced higher levels of pro-tumor properties such as enhanced migration and elevated IL-6 secretion." (PMID 27756885, 2016). "This lack of growth promotion corresponded to the degree of IL-6 knockdown in the individual cell lines with shIL6 #1 showing the greatest degree of IL-6 knockdown and the greatest reduction of tumour growth promotion compared with the control shRFP line." (PMID 27272654, 2016). "For the first time, the anti-tumor role of IL6 in hepatocarcinogenesis was suggested, and NK cells were shown to involve in." (PMID 27556180, 2016). "In conclusion, the present study is the first to report that RT inhibits IL-12 through the IL-6/STAT3 signaling pathway in tumors and tumor-associated DCs." (PMID 26745884, 2016). "In this regard, recent studies revealed that the microbe-driven IL-6 inflammation contributes to tumor progression through Gal1-dependent mechanisms." (PMID 27166189, 2016). "STAT3, known to be important for cancer initiation and tumor progression, was reported to bind directly to the miR-21 promoter upon IL-6 induction." (PMID 27323401, 2016).